NDUFV1 (NADH:ubiquinone oxidoreductase core subunit V1)
Diseases named in the same sentence as NDUFV1 in open-access papers:
NDUFV1 is named in the same sentence as 49 diseases in open-access papers, as found by Europe PMC text mining. Sharing a sentence is not in itself a finding about the gene and the disease. The quoted sentences say what the papers report.
Leigh syndrome (10 papers, 2012 to 2025). "For example, complex I defects induced by Ndufv1 mutations have been shown to be involved in several disorders including encephalopathy, myopathy, and Leigh syndrome." (PMID 37029501, 2023). "NDUFV1 is the nuclear‐encoded structural subunit of complex I. NDUFV1 mutations have been shown to be associated with Leigh syndrome (LS), Leigh‐like syndrome (LL), diffuse leukoencephalopathy, and Parkinson's disease." (PMID 37029501, 2023). "The association of NDUFV1 mutations with Leigh syndrome (LS), Leigh-like syndrome (LL), and diffuse leukoencephalopathy with or without cavitation have been reported." (PMID 33182419, 2020). "Mutations in NDUFV1 can impair mitochondrial respiration, contributing to diseases such as Leigh syndrome, which may involve hearing loss." (PMID 41009448, 2025). "Mutations in the NDUFV1 gene are associated with mitochondrial complex I deficiency and have been linked to various clinical conditions such as Leigh syndrome, severe infantile lactic acidosis, newborn cardiomyopathy, progressive leukoencephalopathy, and other encephalomyopathies." (PMID 40207266, 2025). "Here we present the case of an infant with Leigh syndrome who suffered from a novel heterozygous variant of the NDUFV1 gene, which is phenotypically characterized by a number of previously unknown features." (PMID 39525154, 2024). "One of the more than 100 mutated genes responsible for Leigh syndrome is NDUFV1." (PMID 39525154, 2024). "Leukoencephalopathy seems more prevalent in patients with NDUFS1 and NDUFV1 mutations, but mutations in both genes may also lead to Leigh syndrome." (PMID 22644603, 2012). "Genetic variations and differential expression of NDUFV1 are associated with several human neurological disorders, including Mitochondrial Complex I Deficiency, Parkinson disease (PD), Alzheimer’s Disease (AD), myoclonic epilepsy, schizophrenia, Leigh syndrome and leukoencephalopathy." (PMID 38632500, 2024). "NADH: Ubiquinone Oxidoreductase Core Subunit V1 (NDUFV1) is a nuclear-encoded structural subunit of CI and its mutations are associated with Leigh syndrome (LS), diffuse leukoencephalopathy, and Parkinson’s disease." (PMID 38455045, 2024). "The NDUFV1 gene is located on chromosome 11, and there were five clinical categories linked to mitochondrial complex I deficiency (MCID): Leigh syndrome, severe infantile lactic acidosis, newborn cardiomyopathy, progressive leukoencephalopathy, and an unspecified group of other encephalomyopathies." (PMID 40207266, 2025).
Alzheimer disease (6 papers, 2016 to 2024). A progressive, neurodegenerative disease characterized by loss of function and death of nerve cells in several areas of the brain leading to loss of cognitive function such as memory and language. "In the AppNL-F knockin mouse model of Alzheimer’s disease, increased turnover resulted from imbalances in both synthesis and degradation, converging on proteins associated with synaptic vesicle recycling (Dnm1, Cltc, Rims1) and mitochondria (Fis1, Ndufv1)." (PMID 34979241, 2022).
schizophrenia (6 papers, 2007 to 2024). A major psychotic disorder characterized by abnormalities in the perception or expression of reality. "Previously, we have reported schizophrenia and tissue specific alterations in the expression of complex I subunits, NDUFV1 and NDUFV2, both at the level of mRNA and protein." (PMID 17786189, 2007). "Finally, PRDM14 has key role in modulating specific regulatory functions in schizophrenia, suggesting a possible mechanism for these three TFs to affect these conditions through NDUFV1." (PMID 38632500, 2024). "The present study aimed to investigate the relationship between the clinical features of schizophrenia, and mitochondrial complex activation, based on measurement of mRNA levels in the NDUFV1, NDUFV2, NDUFS1, and UQCR10 genes involved in the peripheral mitochondrial complex." (PMID 25713723, 2014). "Previously, we have shown that in schizophrenia the mRNA and protein expression of the NDUFV1 and NDUFV2 were increased in platelets and lymphocytes as well as in the ventral parieto-occipital cortex, while reduced in the prefrontal cortex as compared with healthy subjects." (PMID 17786189, 2007). "Specifically, mRNA levels of Ubiquinone Oxidoreductase Core Subunit V1 (NDUFV1), NDUFA8, NDUFB9, NDUFS4, NDUFS7, and NDUFV2 were decreased in the frontal cortex of patients with schizophrenia compared with controls." (PMID 37107350, 2023). "In contrast, the mRNA expression of NDUFB2, NDUFB5, and NDUFS4 was decreased in the hippocampus and the mRNAs of NDUFV1, NDUFV2, and NADUFS1 in the striatum of patients with schizophrenia." (PMID 37107350, 2023). "The level of mRNA expression of NDUFV1, NDUFV2, and NDUFS1 was significantly higher in the schizophrenia group than in the control group." (PMID 25713723, 2014). "There was a significant difference in the mRNA level of NDUFV1 (P = 0.003), NDUFV2 (P < 0.01), and NDUFS1 (P = 0.003) between the first-episode schizophrenia patients and control subjects." (PMID 25713723, 2014). "The mRNA level of NDUFV1, NDUFV2, and NDUFS1 in the first-episode schizophrenia patients was higher than that in the controls, and the mRNA level of NDUFV2 was higher in the chronic schizophrenia patients than in the controls." (PMID 25713723, 2014). "Our results suggest that mRNA levels of the NDUFV1, NUDFV2, and NDUFS1 genes of complex I of the mitochondrial electron transport chain might become a possible peripheral marker for the diagnosis of schizophrenia." (PMID 25713723, 2014). "Focusing on the mitochondrial oxidative phosphorylation system (OXPHOS) in schizophrenia, revealed alterations in the enzymatic activities of complexes IV, II and I–III and in mRNA and protein levels of complex I subunits, NDUFV1 and NDUFV2, in post-mortem brain specimens." (PMID 18989376, 2008). "Mithramycin induced a time dependent decrease in mRNA and protein levels of complex I subunits NDUFV1, NDUFV2 and NDUFS1, as well as of reelin, which was arbitrarily chosen as a gene known to be modulated by Sp1 and repeatedly reported to be abnormally expressed in schizophrenia." (PMID 17786189, 2007).
breast carcinoma (5 papers, 2016 to 2025). "We found that NDUFV1 downregulation of CI causes cell cycle arrest in subsets of liver and breast cancer cell lines." (PMID 39873399, 2025). "Of note, inhibition of mitochondrial complex I activity by reduction of core subunit NDUFS3 or NDUFV1 as well as accessory subunit NUDFB9 has been found to enhance the aggressive potential of breast cancer." (PMID 37644092, 2023). "A recent study reported that intracellular CYTL1 is a potential tumor suppressor that stabilizes NDUFV1 to prevent metabolic reprogramming in breast cancer." (PMID 37745303, 2023). "The CYTL1 expression variance contributes to the variance in NDUFV1 expression in breast cancer cells." (PMID 35115484, 2022). "Intracellular CYTL1 plays a previously unappreciated role in regulating metabolic reprogramming, dependent on NDUFV1, in breast cancer." (PMID 35115484, 2022). "Although cell proliferation was affected by the knockdown of other complexes to some extent, NDUFV1 knockdown impaired cell proliferation in all four cell lines tested—two each of breast cancer (MDA‐MB‐231 and MCF7) and hepatocellular carcinoma (HLF and JHH‐4)." (PMID 39873399, 2025). "Additionally, intact CYTL1 abundance positively correlated with NDUFV1 protein levels in the three breast cancer cell lines." (PMID 35115484, 2022). "Thus, regulating intracellular CYTL1 expression and its stabilization of the NDUFV1 protein might be a strategic approach for breast cancer therapy." (PMID 35115484, 2022). "Kaplan–Meier plots indicated that high expression of 4/7 subunits, including NDUFV1, correlated with poor prognosis in patients, specifically, with estrogen/progesterone HR(+)/HER2(−) subtype of breast cancer." (PMID 39873399, 2025). "It has recently been shown that in breast cancer cells, CYTL1 is a tumor suppressor that keeps NDUFV1 stable and prevents metabolic reprogramming." (PMID 37745303, 2023). "Therefore, NDUFV1 and SIRT3/7 have emerged as promising therapeutic targets against this breast cancer subtype." (PMID 39873399, 2025).
Leukoencephalopathy (4 papers, 2012 to 2024). This term describes abnormality of the white matter of the cerebrum resulting from damage to the myelin sheaths of nerve cells. "Progressive cavitating leukoencephalopathy has been described in patients with pathogenic variants in NDUFV1, as well as the nuclear genes NDUFS1, NDUFV2, and NDUFA1, which are also involved in the formation of complex I subunits." (PMID 36163075, 2022). "Our report is the first comprehensive description of the neuropathology in a patient with compound heterozygous variants in the NDUFV1 gene and progressive cavitating leukoencephalopathy." (PMID 36163075, 2022). "Pathogenic variants in the NDUFV1 gene, which codes for complex I of the mitochondrial respiratory chain, have been associated with a variety of clinical phenotypes, including a progressive cavitating leukoencephalopathy." (PMID 36163075, 2022).
lactic acidosis (2 papers, 2020 to 2025). Metabolic acidosis characterized by the accumulation of lactate in the body. "Biochemical and functional analyses revealed lactic acidosis, complex I (CI) assembly and enzyme deficiency, and a loss of NDUFV1 protein." (PMID 33182419, 2020).
leukodystrophy (2 papers, 2020 to 2022). Leukodystrophies are a group of rare, progressive, metabolic, genetic diseases that affect the brain, spinal cord and often the peripheral nerves. "The known NDUFV1 c.1156C > T mutation is mostly associated with leukodystrophy, or LS with brainstem involvement." (PMID 33182419, 2020). "There are cases reported to be associated with leukodystrophy and myoclonic epilepsy, and episodic leukoencephalopathy due to NDUFV1 mutations." (PMID 33182419, 2020). "The present case highlights a subject with biallelic NDUFV1 mutations with leukodystrophy and clinical and radiological evidence of LS and LBSL." (PMID 33182419, 2020).
bipolar disorder (1 paper, 2008). A disorder of the brain that causes unusual shifts in mood, energy, activity levels and the ability to carry out day-to-day tasks. "In bipolar disorder a reduction in the expression level of mitochondrial genes, including those of the OXPHOS was observed in hippocampal and prefrontal postmortem specimens, while an increase in complex I subunits NDUFV1 and NDUFV2 was observed in the parieto-occipital cortex." (PMID 18989376, 2008).
breast tumours (1 paper, 2023). "Therefore, we analysed the expression of 6 genes from the OXPHOS signature (AIFM1, NDUFV1, NDUFAB1, NDUFA7, NDUFS6 and MRPS12) among the most enriched in metastatic samples, by RT-PCR in specimens of 503 breast tumours patients with a follow-up of 20 years." (PMID 37452026, 2023).
cystic teratoma (1 paper, 2024). "Increased intact (positive) NDUFV1 protein expression of mature cystic teratomas of the ovary indicated that NDUFV1 is a factor in induced differentiation." (PMID 38907278, 2024). "In summary, amplifications of EVX2, HOXD13, HOXD12, HOXD11, HOXD10, and HOXD9 on 2q31.1, NDUFV1 on 11q13.2, and RPL10, SNORA70, DNASE1L1, TAZ, ATP6AP1, and GDI1 on Xq28 were found in all nine mature cystic teratomas in this study." (PMID 38907278, 2024). "Amplifications and deletions of large DNA fragments were observed in some samples, while amplifications of EVX2 and HOXD9-HOXD13 on 2q31.1, NDUFV1 on 11q13.2, and RPL10, SNORA70, DNASE1L1, TAZ, ATP6AP1, and GDI1 on Xq28 were found in all nine mature cystic teratomas." (PMID 38907278, 2024).
Macrocephaly (1 paper, 2014). Occipitofrontal (head) circumference greater than 97th centile compared to appropriate, age matched, sex-matched normal standards. "Participant 178 is a 14-month-old male with macrocephaly and two ROHs on chromosomes 2 and 11 involving the HSPD1, PACS1, NDUFV1, and NDUFS8 genes that may play a role in psychomotor delay, hypotonia, and atypical development." (PMID 25400949, 2014).
melanoma (1 paper, 2024). A malignant, usually aggressive tumor composed of atypical, neoplastic melanocytes. "LONP1 over-expression results in impaired complex I assembly in melanoma cells, upregulation of NDUFB6,8,10 and 11, and downregulation of NDUFV1, NDUFV2, NDUFS3 and NDUFS7." (PMID 38263327, 2024).
myocardial infarction (1 paper, 2024). Gross necrosis of the myocardium, as a result of interruption of the blood supply to the area, as in coronary thrombosis. "Our study identified key genes (Aco2, Atp5a1, Ndufs3, and Ndufv1) associated with mitochondrial function in myocardial infarction." (PMID 39775580, 2024). "Ventricular expression of 10 central MitoDEGs (Aco2, Atp5a1, Ndufs3, Ndufv1, Cyc1, Suclg1, Sdha, Sdhb, Cs, and Ndufs2) was verified in a mouse model of myocardial infarction using PCR." (PMID 39775580, 2024). "Besides this, a total of 4 key genes were identified, Aco2, Atp5a1, Ndufs3 and Ndufv1, which were consistent with the expression trend of the mouse myocardial infarction model we constructed." (PMID 39775580, 2024).
myocardial ischemia (1 paper, 2024). A disorder of cardiac function caused by insufficient blood flow to the muscle tissue of the heart. "Ndufv1 is a nuclear-encoded structural subunit of mitochondrial respiratory chain complex I. Timely regulation after myocardial ischemia/reperfusion upregulates its expression level." (PMID 39775580, 2024).
neuroblastoma (1 paper, 2007). Neuroblastoma (NB) is the most common solid, extracranial childhood tumor. "Sp1 role in the regulation of complex I subunits, was demonstrated by the ability of the Sp1/DNA binding inhibitor, mithramycin, to inhibit the transcription of NDUFV1 and NDUFV2, in neuroblastoma cells." (PMID 17786189, 2007).
Paralysis (1 paper, 2025). Paralysis of voluntary muscles means loss of contraction due to interruption of one or more motor pathways from the brain to the muscle fibers. "Our case identifies a previously unknown pathogenic effect of the variant ‘c.248C > T’ in the NDUFV1 gene, observed in a 4-year-old boy with left-sided facial paralysis and balance impairment." (PMID 40207266, 2025).
retinal degeneration (1 paper, 2024). Degeneration of the retina. "Here we show that Gtpx overexpression is highly effective at suppressing retinal degeneration associated with NDUFV1 knockdown, consistent with a role for oxidative stress mediating complex I loss of function neurotoxicity." (PMID 38324746, 2024). "Consistent with our findings with pan-neuronal knockdown, when we knocked down NDUFV1 in the retina using three independent RNAi lines we observed age-dependent retinal degeneration." (PMID 38324746, 2024). "When we reduced levels of NDUFV1 in the retina we observed progressive adult retinal degeneration." (PMID 38324746, 2024).
tumor (9 papers, 2017 to 2025). "In summary, our study proposes the following model: knockdown of APRC4 or NDUFV1 in GBM cells leads to the upregulation of the immuno-stimulatory factor TNFSF15 in tumor cells." (PMID 38561797, 2024). "Through large-scale CRISPRi screening, we discovered genetic modifiers in GBM cells, including ARPC4, PI4KA, ATP6V1A, UBA1, and NDUFV1, that regulated the efficacy of CAR T cell-mediated tumor killing." (PMID 38561797, 2024). "Furthermore, we discovered that TNFSF15 was upregulated in both ARPC4 and NDUFV1 knockdown GBM cells and revealed an immunostimulatory role of TNFSF15 in modulating tumor-CAR T interaction to enhance CAR T cell efficacy." (PMID 38561797, 2024). "Additionally, knockdown of key mitochondrial complex I (NDUFV1) and complex II (SDHC) subunits by shRNA in B16ρ0 cells abolished or significantly retarded their ability to form tumours." (PMID 28195532, 2017). "Thus, the upregulated TNFSF15 in tumor cells upon APRC4 and NDUFV1 knockdown may serve as an immune-stimulatory factor for CAR T cells, facilitating their tumor lytic activity." (PMID 38561797, 2024).
cancer (7 papers, 2019 to 2025). A tumor composed of atypical neoplastic, often pleomorphic cells that invade other tissues. "For instance, knockdown (KD) or mutations in core subunits like NDUFV1 or ND2 can promote metastatic behavior in cancer cells." (PMID 38898058, 2024). "In this study, we investigated the germline mutation alterations of ADAM6, SIX3, GNAS, NDUFV1, H19, DEFA4, and ZIM2 genes in 82 pediatric cancer patients treated with cisplatin." (PMID 41009448, 2025). "In particular, oligomycin treatment revealed that the cancer cells stimulate glycolytic ATP production excessively upon inhibition of respiration—NDUFV1 downregulation stimulated glycolysis synergistically with oligomycin." (PMID 39873399, 2025). "In cancer cells, a decrease in CI activity by RNA interference (RNAi) against NADH:ubiquinone oxidoreductase core subunit V1 (NDUFV1) arrested the cell cycle at the G1/S phase, accompanying upregulation of p21Cip1 cyclin‐dependent kinase inhibitor expression." (PMID 39873399, 2025). "The silencing of NDUFV1 significantly decreased cancer cell number without affecting viability." (PMID 39873399, 2025).
mitochondrial disease (2 papers, 2020 to 2021). "This work presents three patients with clinical presentation of mitochondrial disease with mutations in the NDUFV1 gene." (PMID 34807224, 2021). "Here we described three cases of mutations in the NDUFV1 subunit, associated with mitochondrial disease and possibly CI deficiency." (PMID 34807224, 2021). "This is the case of an infantile-onset LS/LBSL associated with NDUFV1 mutations, which provides further information on the phenotypic variability of mitochondrial diseases caused by NDUFV1 mutations." (PMID 33182419, 2020). "This study highlights the phenotypic variability of mitochondrial disorders caused by NDUFV1 mutations and underscores the importance of molecular diagnosis for mitochondrial diseases." (PMID 33182419, 2020).
kidney diseases (1 paper, 2023). "Therefore, targeting mitochondrial complex I (such as NDUFV1) should be a promising way for dealing with kidney diseases including AKI." (PMID 37029501, 2023). "Overall, our data indicate that NDUFV1 has an ability to maintain mitochondrial homeostasis in AKI, suggesting therapies by targeting mitochondria are useful approaches for dealing with mitochondrial dysfunction associated renal diseases such as AKI." (PMID 37029501, 2023).
NDUFV1 also shares sentences with these, for which no sentence is quoted: Parkinson disease (6 papers); Huntington disease (4); Neurological Disease (3); acute myocardial infarction (1); atherosclerosis (1); basal ganglia disorder (1); Brain atrophy (1); brain diseases (1); coenzyme Q10 deficiency (1); Cognitive impairment (1); diabetes (1); encephalomyopathies (1); Encephalopathy (1); glioblastoma (1); hepatocellular carcinoma (1); infection (1); lung adenocarcinoma (1); lung carcinoma (1); major depression (1); mitochondrial encephalomyopathies (1); Mitochondrial encephalopathy (1); myoclonic epilepsy (1); myopathy (1); Nystagmus (1); paranoid personality disorder (1); Respiratory insufficiency (1); teratoma (1); thyroid cancer (1).